IGF1R (insulin like growth factor 1 receptor)
Diseases named in the same sentence as IGF1R in open-access papers (continued):
Sharing a sentence is not in itself a finding about the gene and the disease.
tumor (continued). "The treatment of blocking antibody of IGF-1R remarkably decreased IGF-1R phosphorylation and downstream activation of Akt and Erk1/2, hereby inhibiting tumour growth and causing tumour regression in SCID mice model." (PMID 18781172, 2008). "On the basis of former results of IGF-1R expression of primary site or possible circulating tumour cells in many cancers, targeting therapy with IGF-1R antibody was enormously developed within recent years." (PMID 18781172, 2008). "In our previous study, we assessed the effect of local IGFBP-4 gene therapy on a previously established subcutaneous cancer model and found that the IGFBP-4 and IGF-1R were overexpressed by the tumours." (PMID 17988381, 2007). "We propose that ST-3 induction in tumour fibroblasts leads to the stimulation of the IGF-1R pathway in carcinoma cells, thus enhancing their proliferative capacity." (PMID 17233884, 2007). "High levels of IRS-1, a major signaling molecule downstream of the IGF-1R, are correlated with tumor size and shorter disease-free survival in estrogen receptor-positive breast cancer patients." (PMID 16457688, 2005). "This property of IGF-1R also implicates the function of this receptor in tumour progression since the degree of anchorage independency reflects the level of malignancy." (PMID 15956962, 2005). "IGF-1R is crucial for tumour transformation and survival of malignant cell, but is only partially involved in normal cell growth." (PMID 15956962, 2005). "This means that metastasis has acquired more anchorage independency, and more IGF-1R dependency, compared to the primary tumour." (PMID 15956962, 2005). "IGF-1R inhibition compromises canonical DSB repair and re-sensitises resistant cancer cells to therapy, supporting its potential as a therapeutic strategy in homologous recombination-deficient tumours." (PMID 42095258, 2026). "Given that IGF1 and IGF1R can also be expressed by tumor cells and influence oncogenic processes both in GH-dependent and GH-independent manners, their expression levels may further complicate the assessment of the activity of the GH pathway in UC." (PMID 40806252, 2025). "Furthermore, monitoring circulating tumor DNA for signs of emerging IGF1R pathway activation, along with serial plasma measurements of stromal IGF1, offers a promising non-invasive strategy for tracking disease progression." (PMID 41275311, 2025). "For instance, targeting hepatocyte growth factor (HGF)-MET or IGF-1/IGF-1R signaling pathways—both critical for maintaining DTP states mediated through tumor-associated fibroblasts (CAFs) and tumor-associated macrophages (TAMs)—has shown promise in preclinical models." (PMID 40894234, 2025). "We next investigated whether RTx- and oHSV-induced activation of IGF1R signaling sensitizes tumor cells to IGF1R-targeted therapy." (PMID 41510300, 2025). "Notably, the triple combination of oHSV, RTx, and IGF1R blockade yielded synergistic anti-tumor effects, abolished YAP1 expression, and significantly enhanced survival in orthotopic BC and GBM models." (PMID 41510300, 2025). "The IGF1/IGF1R system dysregulation is involved in the proliferation of numerous tumours as well as the IGF1/IGF1R system inhibition by statins, which may be of preventive and/or therapeutic value in some tumours such as prostate." (PMID 40874517, 2025). "While we previously demonstrated that IGF2 contributes to immune evasion, the impact of oHSV-induced IGF1R activation on tumor cell signaling remains unclear." (PMID 41510300, 2025). "The binding of IGF-1 to IGF-1R triggers PI3K pathway upregulation in tumor cells." (PMID 40427130, 2025). "Additionally, studies have shown that IGF-1 overexpression can enhance MYC expression, and MYC also can promote tumor cell growth through paracrine signaling mediated by the IGF-1/IGF-1R axis." (PMID 40160318, 2025).
tumor (continued). "Furthermore, cancer-associated fibroblasts (CAFs) were identified as the major source of IGF1 in CCA microenvironment, essential for IGF1R-driven tumor progression." (PMID 41275311, 2025). "Similarly, overexpression of IGF1R markedly exacerbated tumor growth, treatment with surufatinib significantly reduced tumor burden in oeIGF1R-expressing mice, an effect that was further enhanced by the addition of the IGF1R inhibitor linsitinib." (PMID 41275311, 2025). "The combined inhibition of IGF-1R and SFKs (via dasatinib) produced enhanced anti-tumor effects in vitro and in vivo, indicating that dual targeting may yield improved therapeutic outcomes." (PMID 40508013, 2025). "Notably, IGF1R activation persisted within both virus-infected and surrounding tumor areas despite extensive necrosis." (PMID 41510300, 2025). "Tumor-associated macrophages and fibroblasts secrete cytokines that transform normal tumor cells into CSCs via TGF-β1, STAT3/Sox2, JAK2/STAT3/snail, notch/STAT3, and IGF-II/IGF1R pathways." (PMID 39753364, 2025). "↓ brain metastasis and tumor growth in vivo via PCAT6/IGF2BP2/IGF1R pathway." (PMID 41157107, 2025). "Importantly, neutralisation of secreted IGF1 or genetic ablation of IGF1R in tumor cells abrogated these effects, substantiating an essential paracrine loop." (PMID 41275311, 2025). "Notably, elevated IGF1R mRNA expression in NSCLC cells implies active tumor-supportive IGF1R-signalling within the TME." (PMID 41515995, 2025). "Rather, PTEN deletion in combination with the IGF1R silencing may trigger mitogenic processes that ultimately lead to tumor malignancy." (PMID 40115165, 2025). "IGF1R, as a receptor for many exogenous factors, activates a series of signaling pathways upon binding to its ligands, promoting invasion, proliferation, and inhibiting apoptosis, thereby exacerbating tumor malignancy." (PMID 40290443, 2025). "Notably, genetic silencing of IGF1R markedly attenuates the tumor-promoting effects of CAF-C7, underscoring IGF1R as a potential therapeutic target." (PMID 41463024, 2025). "Both clinical GBM specimens and tumor-bearing mouse models show high expression of IGF1R." (PMID 40290443, 2025). "tumor cells are unable to synthesize arginine due to argininosuccinate synthetase 1 (ASS1) deficiency, and instead upregulate insulin-like growth factor 1 (IGF-1R) and enhance ASS1 transcription via c-MYC for arginine metabolic reprogramming." (PMID 39925801, 2025). "Furthermore, the regulatory interplay between PTEN, IGF1R, and cell death mechanisms must be clearly delineated to establish a mechanistic framework that underpins their role in tumor response to RT." (PMID 40335491, 2025). "In GC cells, miR-203a-3p can inhibit tumor development by negatively regulating IGF-1R expression." (PMID 39125625, 2024). "Further, we demonstrate that oHSV-D11mt infection specifically neutralized IGF2 not IGF1 within the TME, effectively abrogating the resistance conferred by IGF2/IGF1R signaling in both tumor and neutrophils/polymorphonuclear myeloid-derived suppressor cells (PMN-MDSCs)." (PMID 38853689, 2024). "In tumor pathology, IGF1R plays an important role in tumor resistance to antitumor immunity." (PMID 38200153, 2024). "In the FLT3i condition (Midostaurin administration), the FLT3 receptor is inhibited and associated with a Boolean value of 0, whereas IGF1R and TNFR remain constitutively active to reflect the environmental background that sustains tumor growth and proliferation." (PMID 38564252, 2024). "This technique offers an advantage over those directly targeting IGF-1R, as mAbs neutralize ligands outside the tumor microenvironment, while cell-related neutralization of the receptor allows for penetration within the tumor via receptor endocytosis and subsequent degradation in the lysosome." (PMID 39273251, 2024).
tumor (continued). "Moreover, in vivo experiments conducted with an EOC mouse model, with anti-PD-1/IGF1R combined, resulted in lower tumor weight compared to individual treatments." (PMID 39450263, 2024). "GEF could only be released after sequential input of NIR and cathepsin B stimuli, and the ROS produced during PDT promoted the apoptosis of tumor cells and inhibited the activation of the bypass IGF1R signaling pathway." (PMID 39321294, 2024). "Findings from our study were consistent with those in previous studies and further revealed that miR-30a-3p, acting as a tumor suppressor, was directly sponged and downregulated by circ_PPAPDC1A, with upregulation of IGF1R and activation of IGF1R/PI3K/ AKT/mTOR signaling." (PMID 38715012, 2024). "In particular, linsitinib induces tumor cell death through IGF1R pathway inhibition and, at the same time, decreases the expression of CAR T-cell exhaustion markers and increases their central memory profiles without interfering with their cytotoxic activity in vitro." (PMID 38420122, 2024). "Importantly, the synthetic peptide PVILLISFLI disrupted the PrP/c-CBL/IGF-1R combination in vitro and in vivo, thus reducing cancer cell autophagy and tumor aggressiveness." (PMID 39130630, 2024). "Among these genes, IGF1R, a well-known tumor suppressor, exhibited a high prediction score." (PMID 38715012, 2024). "Since IGFBP5 is reported as a direct transcriptional target of HIF1α, it may serve as a feedback mechanism for tumours to inhibit IGF1R signalling in adjacent normal cells." (PMID 38886900, 2024). "Also, combining an IGF-1R monoclonal antibody and rapamycin led to complete tumor regression in pediatric sarcoma, surpassing the effects of single therapeutic agents that only induced modest growth delay." (PMID 38540176, 2024). "Therefore, appropriate doses of GHRAs that result in IGF1 lowering can be expected to significantly attenuate the tumor-promoting effects mediated by IGF1R activation." (PMID 39000545, 2024). "Consequently, it is imperative to further investigate the activation mechanism of IGF-1R and its downstream signaling pathway in order to identify key molecules driving tumor proliferation." (PMID 38665430, 2024). "Nuclear IGF1R can rescue damaged DNA replication forks, increase cell tolerance to DNA damage, and promote tumor cell proliferation, which may be the mechanism by which nuclear IGF1R promotes tumor development." (PMID 39404930, 2024). "The mechanisms underlying the anti-tumor efforts of EGCG may include the inhibition of epidermal growth factor and IGF/IGF1R signaling pathways as shown in animal and human studies." (PMID 39203871, 2024). "Circulating levels of GH, IGF-1, sex hormones, and THs may directly or indirectly affect the expression levels of IGF-1 and IGF-1R in tumor tissues.TC tends to be more aggressive in children and adolescents with higher GH and IGF-1 levels." (PMID 39104813, 2024). "EGCG was reported to reduce tumor weight by functioning as an IGF1R antagonist in cancer cells." (PMID 38776022, 2024). "Notably, in the mice treated with IGF1R inhibitor, ascites development was relatively delayed to 45 days after tumor cell inoculation." (PMID 39450263, 2024). "The results of our murine study showed that the combination anti-PD1/IGF1R treatment significantly reduced the tumor burden by 40% compared to IGF1R inhibitor and 34% with anti-PD-1 treatments and achieved a higher survival rate compared to the anti-PD1 treatment alone." (PMID 39450263, 2024). "However, it has been shown in a murine model that drugs targeting IGF1R (Insulin-like Growth Factor-1) improve lifespan with a reduction of neoplasm only in females, which aligns with our findings." (PMID 39107837, 2024). "Consequently, antibodies and small molecules targeting IGF-1 and IGF1R have been developed and tested in pre-clinical and clinical models, showing the potential to delay tumor growth and increase sensibility to CT and RT." (PMID 39195514, 2024).
tumor (continued). "The phosphorylation of ERK (left) and expression of IGF1R (right) was decreased in tumor lysates from SK-N-AS and NB-Eb-C1 xenografts treated with trametinib and ganitumab, indicating that the in vitro mechanisms of action of each of these drugs was preserved in vivo." (PMID 39001383, 2024). "These pathways include direct phosphorylation of IGF-1R by tyrosine kinases such as Src, generation of second messengers, metalloprotease-mediated tumor cell invasion, and scaffolding by β-arrestins, all of which contribute to the activation of IGF-1R and its downstream signaling pathways." (PMID 39638246, 2024). "The study showed that miR-150-5p/3p could inhibit tumor migration and invasion both in vitro and in vivo by regulating insulin receptor substrate-1 and Insulin-Like Growth Factor 1 Receptor (IGF1R)." (PMID 39770446, 2024). "Therefore, when IGF1R is overexpressed, as with most tumors, it plays an anti-apoptotic role by promoting cancer cell survival and tumor metastases." (PMID 39001478, 2024). "Long-term consumption of Keto diet reduces insulin levels, which may reduce insulin–insulin-like growth factor 1 receptor–mediated tumor growth and progression." (PMID 38838145, 2024). "Therefore, targeting IGF1R will have a beneficial dual mode of action by inducing tumor cell death and, at the same time, enhancing the anti-tumor immune cell responses." (PMID 38420122, 2024). "IRS-1, the critical molecule downstream of insulin and insulin-like growth factor 1 receptor, can be ubiquitinated by Cul7 E3 ligase, suggesting that this tumor-suppressing activity may be related to Cul7-mediated degradation of IRS-1." (PMID 39852134, 2024). "IGF1R encodes a high affinity receptor of insulin-like growth factor 1 (IGF1) with tyrosine kinase activity, which triggers downstream signaling pathway promoting cellular proliferation, tumor transformation, and the survival of malignant cells." (PMID 39542983, 2024). "Pre-clinical studies have shown significant benefits can be derived from such a combinatorial strategy, suggesting that overcoming treatment resistance requires multifaceted and comprehensive interventions to counteract the tumor-promoting properties of IGF-1R." (PMID 38540176, 2024). "Furthermore, PCAT6 enhances IGF1R mRNA stability via the PCAT6/IGF2BP2/IGF1R RNA-protein trimer, thereby upregulating IGF1R expression and promoting PCa bone metastasis and tumor growth." (PMID 38166703, 2024). "Interestingly, in the present case, both SSTR2 and IGF-1R appeared on the plasma membrane and in the cytoplasm, showing immunoreactivity not only in tumor cells but also in peritumoral structures (blood vessels and stromal cells)." (PMID 39238765, 2024). "Elevated levels of IGF1R expression are known to facilitate tumor metastasis." (PMID 39771106, 2024). "Notably, overexpression of IR-A and IGF-1R facilitated cell proliferation in tumor cells and stimulated cell differentiation in normal tissue cells." (PMID 38331804, 2024). "Therefore, it can be concluded that IGF-1R activation is crucial for the anchorage-independent growth of cancer cells, and it promotes tumor metastasis and the progression of malignancy." (PMID 38540176, 2024). "The influence of modulation of complex niche parameters (e.g., hypoxia, inflammation and extracellular matrix), as well as target SCs (ESCs, germinal SCs, mesenchymal SCs) and CSCs is emphasized, with reference to tumor reprogramming involving IGF-1R signaling." (PMID 36835075, 2023). "In addition, the critical role of the KRASG12D-driven reciprocal AXL/IGF1R-AKT signaling axis was validated in regulating tumor cell proliferation and apoptosis." (PMID 37209817, 2023). "However, the central findings presented here suggest miR-15b’s function as a possible tumor suppressor through its regulation of Igf1r, resulting in a reduction of IGF1R signaling." (PMID 37686596, 2023).
tumor (continued). "Consequently, evidence implicated the IGF1R and its ligands, IGF1, and IGF2, in tumor development and progression including CRC." (PMID 37284192, 2023). "Finally, we used the PLA technique to screen the proximity of ITGAV and IGF1R in archival oropharyngeal and adenoid cystic TMAs containing triplicate cores of tumor and matched normal tissues, when available." (PMID 36968227, 2023). "This suggests that IGF1R is assembled into an activation-signaling architecture in tumor cells that is significantly different from that in normal cells and that IGF1R activation is tightly linked to matrix adhesion, potentially offering unique therapeutic targets." (PMID 36968227, 2023). "IGF1R is highly expressed in tumor tissues in distinct cancers, in which hypoxia would be one of the important stimulus, and IGF1R is potentially responsible for tumor cell growth or metastasis under stress signals, although the underlying mechanism remains needs to be further explored." (PMID 37777542, 2023). "IGF1R was expressed on cancer cells in the primary original tumor from which OCUM13 was derived." (PMID 36324252, 2023). "Silencing of IGFBP-3 expression by promoter hypermethylation in cisplatin-treated tumor cells was reported previously to activate the PI3K/AKT pathway via de-repression of IGF-1R signaling, decreasing tumor cell sensitivity to cisplatin in NSCLC and inducing cisplatin-resistance in NSCLC patients." (PMID 36766747, 2023). "A potential mechanism that might be directly responsible for keeping IGF1R levels below a certain limit involves its transcriptional suppression by anti-oncogenes or tumor suppressors." (PMID 37834331, 2023). "Importantly, disruption of pro-PrP/c-Cbl/IGF-1R complex using a synthetic peptide, induced a reduction of cancer cell autophagy and mitigated tumor aggressiveness." (PMID 37452879, 2023). "IGF1R protects tumor cells from stresses induced by cytotoxic cytokines, hypoxia, oxidative stress, and DNA damage, and downregulation of IGF1R sensitizes tumor cells to apoptosis." (PMID 36968227, 2023). "Indeed, a better prognosis and a lower tumor proliferative rate when IGF1R is less expressed has been demonstrated." (PMID 36979853, 2023). "IGF1R expression is significantly higher in tumor tissue compared with normal-appearing tissue but not GS or pathologic/clinical tumor stage;Strong IGF-1R expression is associated with a borderline significantly increased risk of lethal PCa (HR = 1.7)." (PMID 36831629, 2023). "Indeed, in pre-clinical studies inhibition of IGF-1R with Linsitinib combined with WEE1 (checkpoint) inhibition led to tumor regression of low replication stress Ewing sarcoma tumors." (PMID 37858153, 2023). "Wang Z has reported that miR-203a-3p function as a tumor suppressor by targeting IGF-1R in GC." (PMID 37573302, 2023). "Also several study mentioned miR-133a as a tumor suppressor miRNA which inhibit the GC growth and exert its effect via different target genes such as Sp1, IGF1R, TCF4 and etc42–44." (PMID 37061507, 2023). "Similarly, the inhibition of IGF1R in the HNSCC tumor cells is accompanied by major increases in active p38MAPK and JNK." (PMID 36968227, 2023). "Here we demonstrate that administration of DMBA induced increased expression of IGF-1, IGF-1R, pIRS, and ER in the tumor tissues of obese rats with subsequent activation of downstream molecules in the signaling pathway that could promote tumor development." (PMID 37511200, 2023). "More potential LM progression-related markers were detected in CSF samples than in tumor samples, including PREX2 mutation (P = 0.014), IGF1R mutation (P = 0.034), AR mutation (P = 0.038), SMARCB1 deletion (P < 0.001), SMAD4 deletion (P = 0.0034), and TGF-beta pathway aberration (P = 0.0038)." (PMID 37131253, 2023).